HSPA1A (heat shock protein family A (Hsp70) member 1A)
Diseases named in the same sentence as HSPA1A in open-access papers (continued):
Sharing a sentence is not in itself a finding about the gene and the disease.
immune disease (3 papers, 2010 to 2024). "In KEGG, genes associated with immune disease and system include HLA-DQA1, HIST1H2BL, HIST1H2AL, C2, CFB, HSPA1A, TAP2, HIST1H3Jand ATP6V1G2." (PMID 34367251, 2021).
bacterial infection (2 papers, 2024 to 2025). "In this study, genome-wide identification of the Hsp40 and Hsp70 families of heat shock proteins was performed, and the protein interaction between one pair of chaperones Dnajb1b and Hspa1a, which is involved in the immune response after bacterial infection, was analyzed." (PMID 39063205, 2024).
cardiovascular disease (2 papers, 2023). "Following a literature review, we chose four RBPs (HSPA1A, ZFP36, TRIM21, and P2RX7) that play important roles in the development of cardiovascular diseases for further co-expression analysis." (PMID 37180137, 2023).
inflammation (1 paper, 2022). Aberrant reaction of the microcirculation characterized by movement of fluid and leukocytes from the blood into extravascular tissues. "A better picture of such hypothesis should however be defined by further studies, comparing nasal HSPA1A/B with FeNO also in asthmatic children and in children with other causes of chronic bronchial inflammation." (PMID 35982171, 2022).
neurological disorders (1 paper, 2020). "Actually, heat shock proteins play a central role in the development of neurological disorders, of which the HSP70 family has been shown its functions, and HSPA1A, a member of HSP70 family, has already been associated with ASD." (PMID 33519924, 2020).
HSPA1A also shares sentences with these, for which no sentence is quoted: vitiligo (11 papers); diabetes (4); Pancreatic Cancer (4); Alzheimer disease (3); Coronary Heart Disease (3); gastric cancer (3); Insulin resistance (3); rheumatoid arthritis (3); Glucose intolerance (2); malaria (2); measles (2); Parkinson’s (2); renal carcinoma (2); acute coronary syndrome (1); adenocarcinoma (1); amyotrophic lateral sclerosis (1); Anxiety (1); astrocytomas (1); brain cancer (1); carcinoma in situ (1); cardiac arrest (1); celiac disease (1); CNS tumors (1); colorectal polyp (1); Eb (1); endometrial cancer (1); esophageal squamous cell carcinoma (1); falciparum malaria (1); Fever (1); glaucoma (1).
A further 40 diseases each share a sentence with HSPA1A in 1 paper.